VGLL4 (vestigial like family member 4)
Description:
May act as a specific coactivator for the mammalian TEFs.
Synonyms: Vgl-4; KIAA0121
Tractability: PROTAC: ubiquitination databases record sites on it.
Gene: Protein-coding gene on chromosome 3 (11,556,069 to 11,771,350, reverse strand). Ensembl gene ENSG00000144560.
Subcellular location: Nucleus
Subcellular location (Human Protein Atlas): Nucleoli fibrillar center; Nucleoplasm
Gene Ontology:
Molecular function: protein binding; transcription coactivator binding
Biological process: negative regulation of cell growth; negative regulation of hippo signaling; negative regulation of Wnt signaling pathway; negative regulation of cardiac muscle cell proliferation; negative regulation of DNA-templated transcription; positive regulation of protein catabolic process; regulation of DNA-templated transcription
Cellular component: nucleus
Genetic constraint (gnomAD): Loss-of-function variants: 4 observed, 11.18 expected, observed/expected ratio (o/e) 0.36, 90% interval 0.17 to 0.82. The synonymous counts are far from expectation, so gnomAD's model fits this gene poorly and the ratio says little. Missense variants: 297 observed, 301.96 expected, observed/expected ratio (o/e) 0.98, 90% interval 0.89 to 1.08. Synonymous variants: 181 observed, 129.5 expected, observed/expected ratio (o/e) 1.4, 90% interval 1.24 to 1.58.
Homologues: Orthologues: chimpanzee VGLL4 (99% identical), dog VGLL4 (93% identical), pig VGLL4 (91% identical), macaque VGLL4 (91% identical), mouse Vgll4 (89% identical), rat Vgll4 (88% identical), rabbit VGLL4 (85% identical), guinea pig VGLL4 (82% identical), tropical clawed frog vgll4 (70% identical), zebrafish vgll4b (47% identical), zebrafish vgll4a (35% identical).
Diseases named in the same sentence as VGLL4 in open-access papers:
VGLL4 is named in the same sentence as 51 diseases in open-access papers, as found by Europe PMC text mining. Sharing a sentence is not in itself a finding about the gene and the disease. The quoted sentences say what the papers report.
gastric cancer (16 papers, 2015 to 2024). A primary or metastatic malignant neoplasm involving the stomach. "Meanwhile, increasing evidence has implicated VGLL4 in human cancer, as reduced VGLL4 mRNA and protein levels were observed in various tumors, such as gastric cancer, lung cancer, esophageal squamous cell carcinoma, and colorectal cancer." (PMID 36522128, 2022). "Abnormal expression of VGLL4 is associated with the development of various cancers, such as lung cancer, gastric cancer and pancreatic cancer." (PMID 31748508, 2019). "The reported YAP antagonists verteporfin and Vgll4-mimicking peptide, which elicit positive effects on tumour growth suppression in liver and gastric cancers, may cause anti-fibrotic effects in an incomplete repair I/R AKI model." (PMID 26574480, 2016). "VGLL4 has been described as a tumor suppressor in many types of cancer, for example in lung cancer, breast cancer, stomach cancer, colorectal cancer, bladder cancer, adenocarcinoma of the pancreas, and squamous carcinoma of the esophagus." (PMID 38255254, 2024). "At present, YAP/VGLL4 balance has been studied in gastric carcinoma, esophageal squamous cell carcinoma, lung cancer and colorectal cancer, but not in HCC so far8,9,11,12." (PMID 29950605, 2018). "Recent studies showed that VGLL4 is a novel negative regulator of YAP-TEADs complex, and a peptide mimicking VGLL4 suppressed tumor growth of human primary gastric cancer in nude mice." (PMID 27412635, 2016). "For the same reason that the YAP/TEAD complex is an important pathway in gastric cancer, VGLL4 and other peptides that specifically inhibit the YAP/TEAD complex are used to treat GC." (PMID 26885617, 2016). "Additionally, a peptide mimicking VGLL4 function has been detected to directly compete with YAP for binding TEADs in gastric cancer." (PMID 30999669, 2019). "For example, a peptide mimicking VGLL4 function blocked the YAP-TEAD interaction and suppressed the growth of gastric cancer in a mouse model." (PMID 32859951, 2020). "VGLL4-mimicking peptide (super TDU) abrogates YAP binding to TEAD4, which has anti-tumor effects in gastric cancer patient-derived cells and in vivo in the gastric cancer mouse model driven by Helicobacter pylori infection." (PMID 31018586, 2019). "VGLL4 is a Hippo pathway member and acts as a YAP agonist; it is said to function as a tumor suppressor in gastric cancer, lung cancer and was also included in a smoking cessation quit-success genotype score calculation." (PMID 28589857, 2017). "Namely, so far, VGLL4 has been investigated as a therapeutical target in triple-negative breast cancer, lung cancer, colorectal cancer, and gastric cancer." (PMID 38255254, 2024). "Through functionally mimicking VGLL4 and subsequently blocking YAP activity, this peptide potently suppresses gastric cancer growth in vitro and in mouse models, including nude mice bearing gastric cancer cells and H. pylori-infected mice." (PMID 33467099, 2021). "Functional in vitro and in vivo studies linked aberrant activation of YAP/TAZ to the progression of gastric cancer (GC), and the inhibition of the YAP/TAZ–TEAD interaction achieved with a Vgl-like-4—(VGLL4) mimicking peptide severely impaired GC cell survival." (PMID 29402328, 2018).
lung carcinoma (11 papers, 2017 to 2025). "Conversely, VGLL4 exerts a tumor-suppressive role in lung cancer, and its upregulation is associated with a favorable prognosis in colorectal cancer." (PMID 38544827, 2024). "VGLL4 gene expression is reduced in lung cancer and its increased expression suppresses proliferation of lung cancer cells by suppressing TEAD transcription." (PMID 41347094, 2025). "VGLL4 acts as a tumor suppressor in lung cancer cells, and it competes with YAP to bind to TEAD4 and inhibits the downstream transcription of TEAD412." (PMID 31748508, 2019). "Interestingly, if this secondary TONDU domain is deleted, it prevents VGLL4 from inhibiting lung cancer cell growth by attenuating YAP/TAZ activity." (PMID 41347094, 2025). "We have previously identified VGLL4 in mice and its homolog SdBP in Drosophila that competes with YAP for TEADs binding, which results in the inhibition of YAP-induced overgrowth and tumor genesis in gastric and lung cancer." (PMID 30789911, 2019).
breast carcinoma (8 papers, 2017 to 2025). "In breast cancer, diminished VGLL4 levels correlate with shorter relapse-free and disease-specific survival, highlighting its role as an independent prognostic factor." (PMID 39857952, 2025). "Hypermethylation of Vestigial-like family member 4 (VGLL4)—a key gene taking part in the inhibition of breast cancer cells’ proliferation, migration, and tumor growth—served indirectly as an indicator of tamoxifen resistance." (PMID 39201247, 2024). "Taken together, these studies are consistent with the findings of the current study and further highlight the important role VGLL4 plays in restraining the oncogenic potential of YAP in breast cancer." (PMID 28733631, 2017). "We present here both clinical and experimental evidence indicating that VGLL4 is a candidate tumor suppressor gene that operates by restraining oncogenic YAP-dependent responses promoting breast cancer progression." (PMID 28733631, 2017). "Low VGLL4 gene expression in clinical breast cancer specimens correlated with a poor patient prognosis." (PMID 28733631, 2017). "Together, our results suggest that VGLL4 regulates several important characteristics of tumorigenesis, functionally suppresses breast cancer growth, migration, invasion in vitro and tumor formation in vivo." (PMID 28733631, 2017). "By combining multi-genomic data from patient tumors with functional studies in breast cancer cell lines and tumor models, we report that VGLL4 functions as a novel suppressor of breast tumor growth and malignant progression." (PMID 28733631, 2017). "Given clinical data linking aberrant VGLL4 expression to breast cancer development and progression, we next explored the functional relevance of VGLL4 expression on breast cancer cell proliferation and migration in vitro and tumor growth in vivo." (PMID 28733631, 2017). "Future studies are required to address the possibility of targeting VGLL4-YAP in breast cancer as a means of selectively modulating genes under the control of TEAD transcription factors." (PMID 28733631, 2017). "To gain insight into the role of VGLL4 as a candidate tumor suppressor in breast cancer, we compared the global transcription profile of VGLL4-overexpressing breast cancer cells to control cells." (PMID 28733631, 2017). "To this end, we overexpressed VGLL4 in two breast cancer cell lines, CAL-51 and CAL-120, that express relatively low but detectable levels of VGLL4." (PMID 28733631, 2017). "In addition, the expression of VGLL4 in breast cancer cell lines (MDA-MB-231, MDA-MB-468, MDA-MB-436, MCF-7, BT-549, T-47D, HCC1937) was lower than that in the human normal breast cell line MCF-10A." (PMID 31748508, 2019). "More importantly, these findings also suggest that VGLL4 may play complex and context-dependent roles in the regulation of breast cancer cell survival and death, a question that currently remains unexplored." (PMID 28733631, 2017). "Collectively, these results establish a clear role for VGLL4 in breast cancer and as such may have broad implications, both as a novel prognostic biomarker and a target for future therapeutic applications." (PMID 28733631, 2017). "Finally, to extend our observations, we used shRNA targeting VGLL4 to efficiently knockdown endogenous VGLL4 in T47D, a breast cancer cell line that expresses high levels of VGLL4." (PMID 28733631, 2017). "In contrast to mammary carcinoma cells, VGLL4 overexpression in either immortalized MCF10A cells derived from benign proliferative breast tissue or primary human mammary epithelial cells did not dramatically influence in vitro growth or tumorigenic potential (data not shown)." (PMID 28733631, 2017). "Furthermore, comparisons of relative VGLL gene expression revealed VGLL3 and VGLL4 were abundantly expressed across different breast cancer subtypes." (PMID 28733631, 2017).
breast carcinoma (continued). "Additionally, we further demonstrate that overexpression of VGLL4 reduces breast cancer cell proliferation, migration, intravasation/extravasation potential, favors cell death, and suppresses tumor growth in vivo." (PMID 28733631, 2017). "VGLL4 may be a promising therapeutic target in breast cancer." (PMID 28733631, 2017). "A weak negative correlation was observed between EZH2 and its targets in breast cancer cell lines MERAV dataset (except for POMT2 and VGLL4 where a positive correlation was detected)." (PMID 30760814, 2019). "In MDA-MB-231 breast cancer cells, reduced mRNA expression of EZH2 was detected upon DZNepA treatment whereas increased expression of its target genes (except POMT2 and VGLL4) was found." (PMID 30760814, 2019). "KM plotter analysis showed improved relapse-free survival with increased expression of PMEPA1, POMT2, VGLL4 and SUMF1 in breast cancer patients indicating their therapeutic potential." (PMID 30760814, 2019). "Upon EZH2 knockdown, fold change in the target gene expression for GPNMB, CoL5A1, POMT2, PMEPA1, VGLL4 and SUMF1 was found to be 1.3, 2.8, 2.2, 2, 1.7 and 1.8, respectively in MCF-7 breast carcinoma cells as detected by qPCR." (PMID 30760814, 2019). "Here, we detected two isoforms of VGLL4, VGLL4-001 (ENST00000273038) and VGLL4-003 (ENST00000430365) in MCF7 breast cancer cells." (PMID 28642487, 2017). "As predicted, VGLL4 had a dramatic suppressive growth effect on CAL-120 and T47D cell lines (YAP-hyper-activated breast cancer cell lines)." (PMID 28733631, 2017). "Tumor grade independent but a significant difference in expression of VGLL4 was detected in ER positive and negative breast cancer cells." (PMID 30760814, 2019). "A protein with inhibitory functions of the YAP-TEAD transcriptional complex is Vestigial Like Family Member 4 (VGLL4), which is a direct competitor for TEAD4 binding that promotes growth-dependent YAP, thus suppressing lung tumor cell growth and regulating breast cancer pathogenesis." (PMID 34205830, 2021). "Here, we report that diminished VGLL4 expression, but not VGLL1-3, correlated with both shorter relapse-free survival and shorter disease-specific survival of cancer patients with different molecular subtypes of breast cancer." (PMID 28733631, 2017). "Furthermore, dysregulation of VGLL4 expression, but not VGLL1-3, is commonly observed in patients with different molecular subtypes of breast cancer and correlated with a poor patient prognosis." (PMID 28733631, 2017).
colorectal cancer (7 papers, 2017 to 2025). A primary or metastatic malignant neoplasm that affects the colon or rectum. "Our findings support the growing evidence that low expression of VGLL4 is associated with poorer survival outcomes in various cancers, particularly breast and colorectal cancer." (PMID 39857952, 2025). "The expression of VGLL4 is significantly downregulated in clinical colorectal carcinoma (CRC) specimens, positively associated with patient survival rate, and inversely correlated with the expression of Wnt target genes in CRCs." (PMID 28051067, 2017). "Similarly, in colorectal cancer, reduced VGLL4 expression is linked to worse survival and inversely associated with Wnt/β-catenin target gene expression." (PMID 39857952, 2025). "The expression of AIFM3, WNT4, and VGLL4 in relation to microsatellite instability (MSI) status in colorectal cancer was analyzed using a cohort of 108 patients extracted from the TCGA colon and rectal cancer (COADREAD) study in the XENA database." (PMID 39857952, 2025). "Subsequently, we examined the effect of VGLL4 on Wnt/β-catenin signalling in human colorectal cancer cell lines HCT116 and SW480." (PMID 28051067, 2017). "Interestingly, VGLL4 blocks the formation of the TCF4–TEAD4 complex and applying a VGLL4–TDU peptide mitigates colorectal carcinoma growth in mice." (PMID 36139407, 2022). "This study provides novel findings highlighting the expression levels of three important apoptotic and growth signaling proteins, AIFM3, VGLL4, and WNT4, involved in different clinically relevant stages of progression in patients with colorectal cancer (CRC)." (PMID 39857952, 2025). "Here, the authors show that VGLL4, a known YAP antagonist, also negatively regulates Wnt/β-catenin signaling by targeting TEAD-DNA-TCF4 complex, thereby inhibiting colorectal cancer growth." (PMID 28051067, 2017). "Furthermore, significant variations in expression profiles and functional characteristics of key components (including VGLL4, NF2, and RASSF family members) have been documented across various malignancies (e.g., breast, hepatic, and colorectal cancers)." (PMID 40486910, 2025). "Therefore, this study highlights the clinical potential of AIFM3, VGLL4, and WNT4 in colorectal cancer (CRC) progression." (PMID 39857952, 2025).
pancreatic cancer (5 papers, 2016 to 2021). "For example, in a mutagenic screen, VGLL4 was a gene identified as a potential candidate tumor suppressor in human pancreatic cancer, and VGLL4 expression was significantly associated with patient survival." (PMID 28733631, 2017). "In pancreatic cancer, it was also observed that CDK1 can phosphorylate Vgll4, which in consequence activates the Hippo and Wnt pathways." (PMID 29903985, 2018).
esophageal squamous cell carcinoma (4 papers, 2017 to 2023). Esophageal squamous cell carcinoma (ESCC) is a type of esophageal carcinoma (EC) that can affect any part of the esophagus, but is usually located in the upper or middle third. "As esophageal squamous cell carcinoma progresses, VGLL4 expression is downregulated." (PMID 28589857, 2017). "MiR-130b also inhibits tumor suppressor function in esophageal squamous cell carcinoma by repression of PTEN and SASH1, and in bladder cancer by targeting VGLL4." (PMID 36701370, 2023). "Decreased expression level of VGLL4 has been observed in multiple types of tumors including gastric cancer, lung cancer, breast cancer, colorectal cancer, and esophageal squamous cell carcinoma (ESCC)." (PMID 31799250, 2019).
cardiac hypertrophy (3 papers, 2014 to 2019). "Further studies showed that loss of VGLL4 in endothelial cells resulted in abnormal arterial valves morphology and developed severe cardiac hypertrophy in 36-week-old (aged) mice, while semi-knockout of YAP rescued heart malformation induced by VGLL4 deletion." (PMID 30789911, 2019). "Although endothelial-specific VGLL4 knockout mice (Tie2Cre+;Vgll4fl/-) could survive, these mice developed severe cardiac hypertrophy at 36 weeks of age." (PMID 30789911, 2019).
gastric tumor (3 papers, 2019 to 2020). "Low expression of VGLL4 positively correlated with poor prognosis of gastric tumor patients, and reduction in VGLL4 expression increased YAP-mediated TEAD activity and gastric tumor cell growth." (PMID 32793503, 2020). "TONDU peptide derived from VGLL4 was earlier shown to inhibit gastric tumors in mouse xenograft models." (PMID 32540914, 2020). "VGLL4 also suppresses EMT in gastric tumors by inhibiting WNT/β-catenin signaling via repression of the nuclear accumulation of β-catenin and activation of TCF/LEF target genes." (PMID 32793503, 2020). "The administration of this peptide significantly repressed YAP activation and gastric tumor growth, indicating that the targeting of YAP/TAZ-TEAD complex by the VGLL4-mimicking peptide is a promising therapeutic strategy for various tumors." (PMID 32793503, 2020). "MiR-222 repressed VGLL4 expression and in turn activated YAP-TEAD signaling and cell growth in gastric tumor cells." (PMID 32793503, 2020). "Strikingly, Zhou’s group designed a peptide mimicking the role of VGLL4 (an inhibitor for the YAP-TEAD interaction) to suppress the tumor growth in both xenograft and carcinogen-induced murine gastric tumor models." (PMID 31175271, 2019).
hepatocellular carcinoma (3 papers, 2018 to 2023). A malignant tumor that arises from hepatocytes. "Actually, adenovirus-mediated transfer of VGLL4 into hepatocellular carcinoma cells selectively killed the tumor cells through cell cycle arrest and apoptosis induction." (PMID 32793503, 2020). "MiR-301a-3p, which repressed VGLL4 expression, was enhanced in human hepatocellular carcinoma tissues and cell lines, and higher miR-301a-3p expression showed positive correlation with poor prognosis in tumor patients." (PMID 32793503, 2020). "Serotonin 5-hydroxytryptamine could control YAP/VGLL4 balance and promote hepatocellular carcinoma progression." (PMID 32793503, 2020). "As a result, 5-HT might contribute to the progression and poor prognosis of hepatocellular carcinoma via regulating YAP/VGLL4 balance." (PMID 29950605, 2018). "Taken together, 5-HT level might affect prognosis of hepatocellular carcinoma via regulating the YAP/VGLL4 balance." (PMID 29950605, 2018). "However, whether YAP/VGLL4 balance was correlated with hepatocellular carcinoma and regulated by 5-HT was poorly understood." (PMID 29950605, 2018). "Here, we investigated whether 5-HT could affect progression and prognosis of hepatocellular carcinoma (HCC) patients and regulate YAP/VGLL4 balance." (PMID 29950605, 2018).
schizophrenia (3 papers, 2015 to 2024). A major psychotic disorder characterized by abnormalities in the perception or expression of reality. "In males, we found hypermethylation at cg11269166 (METTL8), and in females hypomethylation at cg18096987 (VGLL4) and cg04276536 (CCDC102 A), and hypermethylation at cg11854073 (SLC9A10) to be associated with schizophrenia." (PMID 38503926, 2024).
triple-negative breast carcinoma (3 papers, 2019 to 2024). An invasive breast carcinoma which is negative for expression of estrogen receptor (ER), progesterone receptor (PR), and human epidermal growth factor receptor 2 (HER2). "STAT3, a transcription factor in JAK-STAT signaling, was another target of VGLL4, and binding of VGLL4 to STAT3 repressed its transcriptional activity and cell growth in triple-negative breast cancer." (PMID 32793503, 2020).